EGFR (epidermal growth factor receptor)
Diseases named in the same sentence as EGFR in open-access papers (continued):
Sharing a sentence is not in itself a finding about the gene and the disease.
salivary gland cancer (continued). "In this study, we demonstrate that deletion of genomic PTEN, in particular homogenous deletion, predominantly occurs in salivary gland carcinomas with an increased copy number of EGFR or amplification of HER2." (PMID 22240798, 2012). "In lung and salivary gland carcinomas, high polysomy of EGFR if considered to be FISH-positive and the patients would receive treatment." (PMID 23056620, 2012). "Incomplete clinical trials using epidermal growth factor receptor (EGFR) antagonists have been performed on patients with salivary gland cancer." (PMID 20664595, 2010). "Immunohistochemical studies demonstrated different degrees of EGFR expression in several salivary gland carcinomas, including MECs and adenoid cystic carcinomas (ACCs)." (PMID 18826647, 2008). "EGFR mutations are rare in salivary gland carcinoma, rendering EGFR‐tyrosine kinase inhibitors (EGFR‐TKIs) not the ideal targeted therapy." (PMID 40717694, 2025). "NIR-PIT using the EGFR Affibody–IR700Dye conjugate induced necrotic cell death in EGFR-positive salivary gland cancer cells without causing any damage to the control cells." (PMID 38542206, 2024). "EGFR is expressed in approximately 40–65% of salivary gland cancer cases." (PMID 38542206, 2024). "Another patient with salivary gland carcinoma with an EGFR p.D770N mutation (exon 20) showed no response to treatment and presented new metastases at the first restaging." (PMID 32337094, 2020). "With the knowledge that salivary gland carcinomas express various potential targets such as the epidermal growth factor receptor (EGFR), c-kit, and human epidermal growth factor receptor-2 (HER-2), numerous trials of biologic agents have been conducted since 2003." (PMID 31093341, 2016). "Some researchers suggested that molecular targeted chemotherapy including an anti-HER2 or anti-epidermal growth factor (EGFR)-based regimen might be the most promising strategy for treatment of salivary gland cancers." (PMID 24475740, 2014). "In anti-EGFR/Her2-treated salivary gland cancer patients, a retrospective analysis could elucidate the suggested correlation of the PTEN status with therapy response rates." (PMID 22240798, 2012). "In salivary gland cancer, c-kit, EGFR, and VEGF are representative molecular markers that may predict remnant and recurrent tumors." (PMID 23231994, 2012). "The purpose of this study was to evaluate the gene and protein status of PTEN in a representative cohort of salivary gland carcinomas and to correlate the results to clinicopathological parameters, to long-term survival, and to the gene and protein status of EGFR and HER2." (PMID 22240798, 2012). "Therefore, the use of Affibody may extend the therapeutic prospects of NIR-PIT for the treatment of EGFR-positive salivary gland cancer." (PMID 38542206, 2024). "The finding that EGFR-positive salivary gland cancer can be effectively treated with NIR-PIT using the EGFR Affibody–IR700Dye conjugate may extend the therapeutic prospect of salivary gland cancer treatment." (PMID 38542206, 2024). "Thus, the development of anti-HER2 or anti-EGFR strategies in salivary gland carcinomas could represent a reasonable approach based on a biological rationale." (PMID 18826647, 2008). "A recent study on salivary gland cancer revealed that EGFR activation induces EMT in a Snail-dependent manner, and a study using CRC cells found a high expression of EGFR and the occurrence of EMT following EGFR activation through EGF binding to EGFR." (PMID 32977534, 2020). "For example, there were no available clinical trials accepting salivary gland cancer patients for the approved anti-EGFR therapies, such as afatinib and erlotinib or osimertinib within the UK." (PMID 35267442, 2022). "Although a subset of ~17.9% of AciCCs has been reported to express EGFR, only few clinical trials regarding anti-EGFR therapy in salivary gland carcinomas have been performed and the treatment did not result in significant clinical responses so far." (PMID 33669038, 2021).
salivary gland cancer (continued). "In fact, clinical trials with some inhibitors or antibodies for molecular targets, such as gefitinib (a small-molecule EGFR inhibitor), cetuximab (an anti-EGFR antibody), and trastuzumab (an anti-HER2 antibody), were performed for patients with salivary gland carcinomas." (PMID 24574362, 2014). "Therefore, increased gene copy number of EGFR and amplification or overexpression of HER2 should be a precondition for an anti-EGFR and anti-HER2 therapy in salivary gland cancer, too." (PMID 22240798, 2012). "Different types of salivary gland carcinomas show overexpression and an increased gene copy number of EGFR and HER2 with negative impact on prognosis." (PMID 22240798, 2012). "Interestingly, the EGFR and HER2-Akt-mTOR pathways are activated in salivary gland cancer." (PMID 26449187, 2015). "Moreover, in salivary gland cancer first phase-II trials on targeted therapies have been conducted and revealed that the use of anti-EGFR agents, such as cetuximab and gefitinib, failed to produce obvious response, although the majority of patients showed disease stabilisation." (PMID 22240798, 2012). "Moreover, cetuximab, an anti-EGFR monoclonal antibody, and/or gefitinib, an ATP-competitive EGFR tyrosine kinase inhibitor (TKI), have been studied in various types of salivary gland carcinoma, but not in SDC." (PMID 25343854, 2014).
adenosquamous carcinoma (35 papers, 2009 to 2025). A carcinoma composed of malignant glandular cells and malignant squamous cells. "Our study found a similar incidence of 51.16% EGFR mutations in adenocarcinoma patients, with an additional 25% of adenosquamous carcinoma patients also testing positive." (PMID 39429333, 2024). "Pathological analysis demonstrated adenosquamous carcinoma harbouring EGFR exon 19 deletion and T790M mutation." (PMID 30828454, 2019). "One patient with adenosquamous carcinoma and a low level EGFR exon 18 G719C mutation (2%) responded to first-line erlotinib with stable disease for 18 months." (PMID 29100434, 2017). "The case reported is a young “light” ex-smoker who initially had a localized adenosquamous carcinoma bearing an epidermal growth factor receptor (EGFR) sensitizing mutation." (PMID 26366316, 2015). "In many countries, EGFR mutational analysis is performed exclusively in patients with adenocarcinoma (AC) or adenosquamous carcinoma (ADSQ) in whom the EGFR gene mutations occur more frequently than in other NSCLC types." (PMID 25086987, 2015). "The complexity of diagnosing adenosquamous carcinoma from core needle biopsies and the misidentification of poorly differentiated LUAD as LSCC are reported to underlie the tangible EGFR mutation rates reported in suspected LSCC biopsies." (PMID 41211715, 2025). "Among all patients with positive EGFR-TK (n=24), an overwhelming majority (91.6%, n=22) had adenocarcinoma, while 8.3% (n=2) had adenosquamous carcinoma." (PMID 39429333, 2024). "The patient underwent salvage pulmonary resection, and the pathology revealed adenosquamous carcinoma and wild-type for EGFR and ALK." (PMID 36434641, 2022). "A 59-year-old man with relapsed epidermal growth factor receptor (EGFR) exon 19 deletion-positive stage IA adenosquamous carcinoma after lobectomy was treated with erlotinib and bevacizumab for 1 year followed by erlotinib alone for 1 year." (PMID 30828454, 2019). "In line with a previous report, the few patients with adenosquamous carcinoma and an EGFR-test result (n=7) had a high likelihood of a positive result (57%)." (PMID 29100434, 2017). "The aim of our study was to assess EGFR-mutations and ALK-rearrangements in different intratumor subtypes and/or growth patterns in a series of mixed adenocarcinomas and adenosquamous carcinomas." (PMID 26422230, 2015). "High-level EGFR expression (EGFR immunointensity of 2+ or 3+) was observed in only 2.0% (1 out of 52) of the analysed cervical adenocarcinomas/adenosquamous cell carcinomas." (PMID 21730982, 2011). "Assessment of EGFR, PDGFRA and VEGFR2 overexpression and activating gene mutations was performed in a cohort of 30 adenosquamous carcinomas of the uterine cervix." (PMID 19563658, 2009). "The objective of this study was to investigate EGFR, PDGFRA and VEGFR2 RTKs overexpression and activating gene mutations in a cohort of 30 adenosquamous carcinomas of the uterine cervix." (PMID 19563658, 2009). "Notably, 22 (91.67%) of the EGFR-TK-positive patients had adenocarcinoma, and two (8.33%) had adenosquamous carcinoma." (PMID 39429333, 2024). "Patient 5 was a 74-year-old female never-smoker with an exon 19 EGFR-mutated stage IIIa (cT4N0M0; T4 due to tumor size) adenosquamous carcinoma." (PMID 39790537, 2023). "The specimens of the other two EGFR-mutant cases (9%) were classified on biopsies as most likely adenosquamous carcinomas (ADSC), based on the co-existence of cells with mucin production, keratinization and ADC/SCC immunohistochemical markers (CK7+/TTF1+/CK5+/p40+)." (PMID 29899852, 2018). "In a study where lung SQCCs were identified based biomarker expression, EGFR mutations were absent, suggesting SQCCs found to contain EGFR mutations were actually misdiagnosed poorly differentiated ADCs or adenosquamous carcinoma." (PMID 27092882, 2016). "Despite the presence of EGFR overexpression, we showed that none of adenosquamous carcinomas harbour EGFR gene activating mutations." (PMID 19563658, 2009).
adenosquamous carcinoma (continued). "The mechanism driving EGFR overexpression in adenosquamous carcinomas remains to be determined." (PMID 19563658, 2009). "Although detailed data regarding mixed histology were not available, a significant proportion of adenosquamous carcinomas, a subtype associated with EGFR mutations and favorable clinical outcomes, could be included within the population." (PMID 38067272, 2023). "EGFR-mutations are extremely rare in pure pulmonary squamous cell carcinomas (SqCCs) and their occasional detection in this type of NSCLC has been ascribed by some authors to the misdiagnosis of cases that are adenosquamous carcinomas, or poorly differentiated LACs." (PMID 31266248, 2019). "Adenosquamous carcinomas usually harbour EGFR activating mutations, whereas MECs do not." (PMID 20664595, 2010). "In conclusion, the present study is most the comprehensive analysis of EGFR, PDGFRA and VEGFR2 oncogenes in adenosquamous carcinoma." (PMID 19563658, 2009). "Immunohistochemical analysis revealed that 6 out of 59 (10.2%) cervical squamous cell carcinomas showed significant amplification of the EGFR locus, whereas none of the 52 adeno/adenosquamous cell carcinomas had detectable EGFR amplification (P<0.05)." (PMID 21730982, 2011). "Furthermore, we found that never-smoker males with adenocarcinoma/adenosquamous carcinoma have a 36% chance of EGFR positivity, with the majority harboring Exon 19 deletion." (PMID 39429333, 2024). "Despite the absence of EGFR and PDGFRA activating mutations, the presence of overexpression of these three important therapeutic targets in a subset of cases may be important in predicting the sensitivity of adenosquamous carcinoma to specific anti-RTKs drugs." (PMID 19563658, 2009).
oropharyngeal carcinoma (34 papers, 2014 to 2026). Carcinoma, predominantly squamous cell, arising from the epithelial cells of the oropharynx. "Another type of cancer in which p16 plays a role is oropharyngeal cancer; indeed, it has been found to be a prognostic factor associated with a better outcome and a decreased epidermal growth factor (EGFR) expression." (PMID 32945604, 2020). "Next, we assessed the association between EGFR overexpression and radioresistance in oropharyngeal carcinoma cells." (PMID 30414263, 2018). "Immunohistochemistry showed that overexpression of both GRP78 and EGFR was associated with a poor prognosis in oropharyngeal carcinoma patients (P<0.05)." (PMID 29232380, 2017). "The issue of EGFR expression deserves a further comment relative to oropharyngeal cancer, given the strong association between these tumor sites and the presence of HPV conferring a favorable prognosis." (PMID 27556186, 2016). "Aberrant EGFR signaling, particularly nuclear localization and overexpression, is strongly linked to aggressive tumor behavior and poor clinical outcomes in breast, thyroid, and oropharyngeal cancers." (PMID 41511366, 2026). "The role of EGFR inhibition in HPV-associated oropharyngeal cancer vs. HPV-negative head and neck cancer remains controversial and may differ depending on whether given as monotherapy or combined with chemotherapy or radiotherapy." (PMID 27843803, 2016). "Based on EGFR-targeted therapy, two clinical trials were performed in the treatment of oropharyngeal carcinoma." (PMID 36209263, 2022). "EGFR has been identified as a predictive biomarker for chemotherapy or radiation/chemotherapy benefits and survival in oropharyngeal cancer and for targeted therapy benefit in HNSCC." (PMID 35371031, 2022). "In oropharyngeal cancer, high expression of p16 was correlated with a decreased EGFR expression, suggesting a relationship between p16 and EGFR activation." (PMID 34227915, 2021). "It was reported that EGFR and pEGFR (phosphorylated epidermal growth factor receptor) are potential biomarkers of prognosis for oropharyngeal cancer." (PMID 34646755, 2021). "Both studies attempt to replace cisplatin by the epidermal growth factor receptor (EGFR) inhibitor cetuximab in patients with HPV positive oropharyngeal cancer." (PMID 31355146, 2019). "In order to exclude a confounding impact of sublocalizations of tumors on the clinical outcome of the four EGFR/EpCAM patient subgroups, we analyzed the most prominent entity, i.e., oropharyngeal carcinomas (n = 105)." (PMID 30261040, 2018). "A Kaplan-Meier survival analysis showed that oropharyngeal carcinoma patients with EGFR and GRP78 co-overexpression had the worst prognosis with respect to overall survival (P < 0.05)." (PMID 29232380, 2017). "Considering the cell lines used in this study were HPV (-) oropharyngeal carcinoma cells, we selected HPV (-) human oropharyngeal carcinoma for the detection of EGFR and GRP78 expression by immunohistochemistry." (PMID 29232380, 2017). "The EGFR-specific mAb cetuximab is one of the most effective treatments for oropharyngeal carcinoma, while patient responses to EGFR inhibitors given alone are modest." (PMID 29232380, 2017). "Whilst overexpression of EGFR has been associated with worse survival in oropharyngeal cancers, previous work has not identified an association between EGFR amplification and survival." (PMID 33804510, 2021). "Our results indicate that miR-133a-3p is a target of smoking-induced changes in HPV(+) patients and alters the expression of EGFR and HuR which may promote HPV associated oropharyngeal cancer." (PMID 30289952, 2018). "Thus, we hypothesized that DSB repair mediates EGFR‐ERS regulated radioresistance in oropharyngeal carcinoma cells." (PMID 30414263, 2018).
oropharyngeal carcinoma (continued). "Interestingly, two of the phase III clinical trials investigating the combination of anti-EGFR therapy with radiotherapy compared to the standard treatment with chemo-radiotherapy for HPV-positive oropharyngeal cancer patients, the RTOG 1026 and the DE-ESCALaTE study, have been recently presented." (PMID 30619735, 2018). "This epidermal growth factor receptor (EGFR) inhibitor showed encouraging results when combined with systemic chemotherapy for recurrent, metastatic or unresectable oropharyngeal cancer." (PMID 39749049, 2024). "The phosphorylation pattern of EGFR with ex20ins resembled that of HPV-related SNSCC and oropharyngeal cancer." (PMID 37109043, 2023). "To further clarify the relationship between EGFR and GRP78 expression and the prognosis of patients with oropharyngeal carcinoma, we divided the patients into four groups: EGFR (-) GRP78 (-), EGFR (+) GRP78 (-), EGFR (-) GRP78 (+) and EGFR (+) GRP78 (+)." (PMID 29232380, 2017). "Our study, for the first time, found that the expression of EGFR and GRP78 in oropharyngeal carcinoma tissue was correlated and that the co-expression of these two proteins indicated a poor prognosis." (PMID 29232380, 2017). "Few data exist on the relationship between EGFR and HPV-induced oropharyngeal cancers." (PMID 31027243, 2019). "Finally, it was revealed by immunohistochemistry that the expression levels of EGFR and GRP78 were correlated and that the co-overexpression of EGFR and GRP78 was correlated with a poor prognosis of oropharyngeal carcinoma." (PMID 29232380, 2017). "Notably, patients with p16+ oropharyngeal carcinoma demonstrated better three-year PFS and overall survival compared to those with p16- oropharyngeal carcinoma, while tumor EGFR expression did not significantly affect the outcome." (PMID 38715609, 2024). "However, in a further study done mostly in oropharyngeal cancer patients, high GLUT1 expression correlated with EGFR expression and p16 negative status but not with SUVmax of the primary tumor." (PMID 32984043, 2020). "The reduction in ANXA1-TYR in oropharyngeal cancer was independent of HPV status, which may reflect the use of the protein by EGFR in the process of inducing cell proliferation independent of whether the etiology of the tumor involves the virus or not." (PMID 24782913, 2014).